ANXA1 (annexin A1)
Diseases named in the same sentence as ANXA1 in open-access papers (continued):
Sharing a sentence is not in itself a finding about the gene and the disease.
tumor (continued). "Therefore, to clarify the status of ANXA1 expression in gastric mucosa is of great value in determining whether ANXA1 is “oncogenic” or “tumor suppressor”." (PMID 25038797, 2014). "Moreover, recent studies have shown that, in PC tissues, localization of ANXA1 was different in cytoplasm and membrane of tumour cells, indicating that the function of ANXA1 may vary among its differential localization." (PMID 25510623, 2014). "However, upregulation of ANXA1 mRNA was observed in 3 of 8 (37.5%) cases, which might be attributable to an abundant accumulation of cells in the tumor tissue compared with the corresponding benign tissue." (PMID 25038797, 2014). "However, in some tumors, Anxa1 is considered to be a tumor suppressor." (PMID 23991102, 2013). "Thus, Anxa1 expression needs to be determined for each tumor type." (PMID 23991102, 2013). "Targeting ANXA1 and ANXA6 is relevant because, where ANXA1 is downregulated/absent, ANXA6 expression can be restored in a compensatory manner, partially sustaining tumor progression." (PMID 41744829, 2026). "ANXA1 interacts with various cell types within the TME, influencing tumor proliferation, invasion, and metastasis." (PMID 40394037, 2025). "Beyond its prognostic and predictive value, ANXA1 may actively regulate the specific interactions within CRC TME compartments, demonstrated by the association between strong ANXA1 expression and tumor-infiltrating immune cells, leading to poor patient survival." (PMID 41283264, 2025). "Supporting these findings, ANXA1 has a critical role in breast oncogenesis, particularly by stimulation of the epithelial–mesenchymal transition (EMT), thereby promoting tumor migration and metastasis." (PMID 41283264, 2025). "ANXA1 is involved in TME regulation, with an impact on tumor proliferation, metastasis, immune evasion, and therapy resistance." (PMID 41283264, 2025). "Immunostimulatory DAMPs include ATP, which is secreted via autophagy-dependent mechanisms, and nuclear or cytoplasmic proteins, such as annexin A1 (ANXA1) and high mobility group box 1 (HMGB1), which are passively released from dying tumor cells." (PMID 40004078, 2025). "Specifically, the interaction between ANXA1 and FPR1 in DCs enhances anti-tumor immunity by promoting the phagocytic uptake of dead cell antigens by DCs." (PMID 41035636, 2025). "Recent evidences show that ANXA1 is upregulated in CRC, exhibiting a strong correlation with an advanced TNM stage, lymph node involvement, and tumor invasion." (PMID 41283264, 2025). "There were several transcripts showing elevated expression in GBM stromal cell types versus stromal cell types in the grade III tumor, including IGFBP2 (ECM glycoprotein), ANXA1 (ECM-affiliated), ITGA7 (integrin), and SRGN (proteoglycan)." (PMID 41366031, 2025). "To understand the mechanisms underlying the altered growth and invasion phenotypes following KO interventions, we performed single-cell profiling of ANXA1-KO, RFX4-KO, and HOPX-KO tumor cells extracted from mouse brains." (PMID 40683881, 2025). "Key proteins identified, including ANXA1, SLC2A1, S100A4, and NFKB1, contribute to tumour progression and the resistance phenotype." (PMID 40004024, 2025). "Both stromal and tumor ANXA1-expressing cells contribute to TME communication by autocrine, paracrine, and juxtacrine signaling pathways, stimulating tumor cell proliferation, disease progression, invasion, metastasis, and resistance to therapy." (PMID 41283264, 2025). "In contrary we found upregulated (EOMES, TNFSFR9, TIGIT, KLRD1) and downregulated genes (PAG1, GNLY, ANXA1, FGFBP2) that are involved in tumor escape from immune surveillance by suppressing T-cells or by reprogramming T-cells toward T-cell exhaustion." (PMID 40079005, 2025). "In the group of ANXA1 knockdown and overexpression of GOT1, tumor formation and growth were restored." (PMID 40390008, 2025). "The ECM-affiliated genes ANXA1 and ANXA2 showed robust spatial enrichment in GBM compared to the grade III tumor." (PMID 41366031, 2025).
tumor (continued). "Recent studies have further elucidated that RRM2 contributes to resistance against docetaxel chemotherapy by stabilizing ANXA1 and activating the PI3K/AKT signaling pathway, thereby enhancing tumor cell survival under chemotherapeutic stress." (PMID 41346575, 2025). "Upregulated EOMES and TNFSFR9 and downregulated genes (PAG1, GNLY, ANXA1, FGFBP2) that are involved in tumor escape from immune surveillance by suppressing T-cells or by reprogramming T-cells toward T-cell exhaustion." (PMID 40079005, 2025). "ANXA1 and MDK are recognized as endogenous anti-inflammatory molecules that suppress immune activity and exacerbate tumor progression." (PMID 40417666, 2025). "The immunosuppressive effects of ANXA1 in CRC are also supported by its interaction with EGFR, a major signaling molecule involved in tumor development and therapeutic resistance." (PMID 41283264, 2025). "In vivo, circMAN1A2 overexpression suppressed tumor growth, enhanced TMZ sensitivity, and reduced NRF2/ANXA1 expression, effects reversed by TEP1." (PMID 40583858, 2025). "The highest tumor-to-control ratio (fold change) was found in T1 and T2 carcinomas for both IGFBP7 and ANXA1 in the array analysis." (PMID 38893148, 2024). "In the context of cancer, ANXA1 has been shown to be involved in STAT3, PI3K and MAPK/ERK signalling pathways which promote tumour initiation and progression." (PMID 38200229, 2024). "Initially, signals from tumor cells to various macrophages in ACP tumor tissues were expressed by ligands for ANXA1 and MIF in tumor cell subtypes, defined as calcification." (PMID 39483146, 2024). "MiR-196b-5p targets genes of the ANXA1 and HOX families in various types of tumors (including CRC), leading to tumor progression." (PMID 39001526, 2024). "Annexin A1 (ANXA1) is externalized through exosomes, leading to the acquisition of a mesenchymal phenotype in both tumor and stromal cells; the complex ANXA1/EVs expedites macrophage recruitment and promotes M2 macrophage polarization." (PMID 40458305, 2024). "The levels of ECM1 and ANXA1 in uEVs were found to be significantly elevated in MMTV-PyMT transgenic mice from week 5 compared to normal mice, with an increase in tumor size." (PMID 39040439, 2024). "The neural network classifier showed a good performance and outperformed an immunohistochemistry-based signature comprising ANXA1 (annexin A1) and ANXA10 (annexin A10) in recognizing iCCA precursor lesions and pCCA, both showing high similarity with the tumor." (PMID 39199659, 2024). "HEYL, SLC2A3, and FBN1 were found to mediate tumor progression and chemoresistance mainly by facilitating angiogenesis and EMT, while CERCAM, ANXA1, and SPOCD1 promoted tumor progression through the PI3K/AKT and EGFR signaling pathways." (PMID 39033778, 2024). "In total n = 8 LSCC and n = 6 control tissue lysate samples (malignancy-free tumor-distant tissue) were analyzed for IGFBP7 and ANXA1." (PMID 38893148, 2024). "Annexin A1 (ANXA1), an emerging candidate, has been used as an EMT regulator in several tumor types." (PMID 37062068, 2023). "Among them, ANXA1 and FKBP11 were highly expressed in tumor tissues compared to normal tissues, whereas BIRC3 and TNIP3 were lowly expressed in tumor tissues." (PMID 37047025, 2023). "By comparing 2D and 3D cell culture techniques regarding the expression of ANXA1, CD44, KRT18, OCT4, and SOX2OT genes, folding results represented variation in gene expression between tumor cells cultivated in 2D and 3D cultures." (PMID 37884554, 2023). "In distinguishing between tumor and normal nodules, the following five proteins showed the best performance: P50479 (PDLIM4), P04083 (ANXA1), P14618 (PKM), P61916 (NPC2), and P02545 (LMNA)." (PMID 36418670, 2023). "ANXA1 was increased in CD8 memory T cell post-treatment, which has been reported to inhibit the anti-tumor immunity and support the formation of an immunosuppressed tumor microenvironment that promotes tumor growth and metastasis." (PMID 36417130, 2023).
tumor (continued). "CXCL10, P2RX7, TLR3, and TLR4 were significantly upregulated in IS2 tumours in the TCGA cohort, whereas ANXA1, CXCL10, FPR1, IFNAR2, P2RX7, and TLR4 showed significantly higher expression levels in IS4 tumours in the GEO cohort." (PMID 36851274, 2023). "As expected, we found that the value of 3 PDEARGs (ANXA1, COL6A1, and PDPN) and key DETF (WWTR1) were co‐expressed significantly higher in the tumor core than in the peripheral of GBM tissue, specifically in the neoplastic cells." (PMID 37434432, 2023). "In our study, we discovered that PI16 plays a vital role in suppressing the development of tumours and the progression of metastasis in BLCA by inhibiting the activity of NF-κB through ANXA1-dependent ubiquitination of NEMO." (PMID 37525118, 2023). "In the cell subsets of tumor samples, FN1, CLU, and ANXA1 were high expressed in tumor cells and low expressed in myeloid cell and fibroblast." (PMID 35359404, 2022). "ANXA1 was highlighted as a biomarker in oncology, and manipulation of ANX1 in cancers can influence the metastatic behavior of the tumor cells by modulating inflammation, immune response, and angiogenesis." (PMID 36147313, 2022). "The exposure of calreticulin and the release of ANXA1, ATP and HMGB1 result in the attraction and maturation of DCs in the tumor microenvironment." (PMID 36015189, 2022). "Here, we aimed to describe the interaction between the AnxA1/FPR1 and the Interleukin-6 (IL-6) signaling pathways and their role in the tumor microenvironment (TME)." (PMID 35626741, 2022). "ICD is mainly characterized by calreticulin (CRT) exposure at the cell surface of dying tumor cells, the release of the ATP, HMGB1 (High-Mobility Group Box 1) and annexin A1 (ANXA1) in the extracellular space." (PMID 36429101, 2022). "AnxA1 also promotes the alternative activation of macrophages, suggesting a role in the formation of an immunosuppressive TNBC tumor microenvironment." (PMID 35897832, 2022). "Injection of 4T1 cells, regardless of the expression of ANXA1, caused weight loss and a significant reduction in overall survival of the mice, suggesting that expression of ANXA1 in 4T1 cells did not significantly affect the tumor growth in the brain, supporting our in vitro observation." (PMID 35382852, 2022). "Precisely, various strategies have already been developed successfully targeting ANXA1 and ANXA2 functions, which have shown efficacy on various preclinical tumor models." (PMID 36247003, 2022). "Regarding the evidence that IL-6 signaling elicits the AnxA1/FPR1 axis leading in TNBC cells, we tested the in vivo effect of this receptor inhibition on tumor growth and fibroblast migration." (PMID 35626741, 2022). "In contrast, several other studies indicated that ANXA1 was upregulated in BLCA and correlated with high pathological grade and tumor progression." (PMID 34991599, 2022). "On the contrary, RBP4 and MIOX were highly expressed in tumour cells 1 from ccRCC2, and ANXA1 and MUC20-OT1 were highly expressed in tumour cells 2 from ccRCC2 but lowly expressed in tumour cells 2 from ccRCC1." (PMID 34168986, 2021). "Moreover, we hypothesize that if the first BNCT treatment upregulates Anxa1 in tumor tissues due to an inflammatory response or induced immunogenicity, more effective 10B accumulation in tumor tissues might occur following the second injection of IF7-10B drugs." (PMID 33446132, 2021). "Taken together, our results revealed that ANXA1 was profoundly upregulated in PTC tissues, whose expression is closely related to tumor size and adverse prognosis in PTC patients." (PMID 33531975, 2021). "The research evidence showed that the expression of ANXA1 is conflicting between different cancer types and ANXA has tumor suppressor and promoter roles in different types of cancers." (PMID 34439260, 2021). "The higher expression of FAM3C, LGALS9, ANXA1, SPP1, CD99 and LAMP1 in tumor tissues compared with normal tissues were confirmed by immunohistochemistry in tumors." (PMID 35087839, 2021).
tumor (continued). "In the present study, we elucidated that ANXA1 was markedly increased in PTC compared with normal thyroid tissues, whose expression is closely related to the larger tumor size and poor survival of PTC patients." (PMID 33531975, 2021). "ShRNA-mediated silencing of ANXA1 suppresses nuclear factor (NF)-kB activity, which results in the direct inhibition of CXCR4 and matrix metalloproteinase (MMP) expression, impeding tumor cell invasion." (PMID 34200100, 2021). "ANXA1 binds formyl peptide receptor 1 (FPR1) thus facilitating DC homing to dying cells in the tumor bed, and CALR stimulates tumor antigen engulfment by DCs." (PMID 33809187, 2021). "Annexins exhibit N-termini unique to each family member and an evolutionarily conserved core domain, and the Anxa1 N-terminal amino acid sequence is completely in mouse and humans, suggesting that IF7 would bind human Anxa1 expressed in the tumor vasculature." (PMID 33446132, 2021). "Tumor parenchyma staining was positive in a majority of NSCLC samples (54 of 80), which is consistent with previous reports of anxA1 expression in lung tumors." (PMID 32497150, 2020). "These tumor cells produce stress-induced ligands (DAMPs): CALR, ATP, ANXA1, and HMGB1, whose activation is conditioned by several constraints." (PMID 33281620, 2020). "Therefore, we highlighted the importance of ANXA1/EVs-FPR axes in PC progression as a vehicle of intercommunication tumor cells-stroma, suggesting a specific potential prognostic/diagnostic role of ANXA1, whether in soluble form or even if EVs are captured in PC." (PMID 33353163, 2020). "Several key proteins such as MAP2K1, ITGB4, ITGA6, PTPN6, FMNL1, ANXA1, and MMP9 that modulate cell motility and tumor cell invasion were upregulated in MIBUC." (PMID 32326232, 2020). "As for the phenomenological model, tumor cells can be converted into dying tumor cells when treated by chemotherapeutic agents, whereas dendritic cells become active after sensing ATP, HMGB1, CALR, and/or ANXA1." (PMID 33281620, 2020). "We used one such antibody for IHC studies to assess the prevalence and extent of vascular anxA1 expression in human NSCLC and normal tissues, as well as in a diverse set of rodent tumor models." (PMID 32497150, 2020). "In addition, it has been hypothesized that anxA1 could act to modulate the tumor immune environment, and anxA1 and its cleavage products are known to modulate neutrophil extravasation and transendothelial migration through interaction with formyl peptide receptors." (PMID 32497150, 2020). "The results presented here provide a comprehensive assessment of vascular anxA1 expression in NSCLC and address the potential of anxA1 as a vascular target for anti-tumor biologics." (PMID 32497150, 2020). "The use of the ANXA1 KO MIA PaCa-2, compared to WT one, was confirmed to be a good in vitro model to preliminarily describe the action of the protein of our interest on tumor microenvironment." (PMID 33353163, 2020). "A 37 kDa protein, annexin A1 (ANXA1), was found to be an anti-inflammatory mediator and expressed by tumor cells." (PMID 32410828, 2020). "Some antitumour drugs release CRT by increasing the production of ROS in tumour cells, phosphorylating PERK/PKR and eIF2α, activating PI3K/AKT pathway, and displacing CRT/Annexin A1 to the cell membrane C/EBPα mRNA binding, promote C/EBPα expression." (PMID 30394654, 2019). "Taken together, this knowledge encouraged us to focus on the down-modulation of miR196a in ANXA1 KO MIA PaCa-2 cells, despite that this kind of correlation appeared inverse in numerous tumour models." (PMID 29986379, 2018).
tumor (continued). "This miRNA is a well known oncogenic factor in several tumour models and it is able to trigger the agents of the epithelial to mesenchymal transition (EMT), like ANXA1." (PMID 29986379, 2018). "These genes are known to be implicated in proliferation (MAPK8), metastatic diffusion of tumor cells (ITGB1), drug resistance (ANXA1), coagulation (ANXA3, ANXA5) or inflammation (HPGD, NFKB1)." (PMID 29228619, 2017). "The PhKh1 primary tumor cells resistant to ATO overexpressed transcripts coding for the molecular chaperones CLU and ANXA1." (PMID 29371980, 2017). "Consistent with this, our study reveals a new dimension between ANXA1 and CCL5 to modulate macrophage polarization and tumour cell proliferation." (PMID 29263330, 2017). "Overall, these data suggest a significant relationship between ANXA1 and CALD1 positivity and early tumor progression after tamoxifen treatment for recurrent ER positive breast cancer." (PMID 26657294, 2016). "In order to confirm our MS findings, we performed IHC stainings of both ANXA1 and CALD1 in an independent cohort of FFPE ER positive tumor tissues captured in a TMA to assess the clinical relevance of these markers." (PMID 26657294, 2016). "ANXA1 and CALD1 staining only were observed in 17 and 16 tumor tissues, respectively, while only 4 tumors showed co-expression of the two markers." (PMID 26657294, 2016). "Besides fMLP, ligands for FPR1 also include non-microbial endogenous host-derived peptides such as mitochondrial formylated peptides fMMYALF, fMLKLIV and fMFADRW, Annexin A1 and Cathepsin G, that may be released by necrotic cells within the tumor microenvironment." (PMID 27432059, 2016). "In these inflammatory cells, we verified a significant up-regulation of ANXA1 and FPR2/ALX expression in the peritumoral and tumor samples compared with the corresponding control tissues." (PMID 25490767, 2014). "Blocking anti-inflammatory mediators like exposed annexin A1 that arise due to treatment induced tumor cell apoptosis could tip the balance from an anti- to a pro-inflammatory tumor environment and, thus, facilitate tumor antigen recognition and tumor rejection." (PMID 23638088, 2013). "In conclusion, wogonin can enhance the immunity of tumor cell vaccine, in which ER stress activated AKT signaling pathway mediated calreticulin/Annexin A1 translocation and/or HMGB1/ATP release are involved." (PMID 23251389, 2012). "In conclusion, the activation of PI3K pathway elicited by ER stress induced CRT/Annexin A1 translocation (“eat me” signal) and HMGB1 release, mediating wogonin-induced immunity of tumor cell vaccine." (PMID 23251389, 2012). "A set of proteins that correlate with the inhibition of tumor growth in the response to therapy included transforming growth factor-β induced (TGFBI), annexin A1 and protein disulfide-isomerase, which were increased." (PMID 21060779, 2010). "Importantly, treatment with an ANXA1-derived peptide (A11) combined with TRKA inhibitors synergistically reversed T cell exhaustion and suppressed tumor growth in preclinical models." (PMID 41954859, 2026). "While ANXA1 is an important player in SCLC’s biology, due to tumor cell heterogeneity and the adaptability of this particularly malignant cancer, its intracellular signaling is probably highly redundant and sprawling, which makes its targeting in future drug trials challenging." (PMID 40361334, 2025). "In summary, in ICC cells with high expression of ANXA1, ANXA1 further increases the adaptability of Glutamine metabolism mediated oxidative stress by stabilizing ubiquitin proteasome mediated GOT1, thereby promoting tumor growth and proliferation." (PMID 40390008, 2025). "We observed that ANXA1-KO U3013MG tumors did not form a bulk tumor as SCR-U3013MG and U3013MG-WT did." (PMID 40683881, 2025). "Additionally, we identified key proteins, including ANXA1, SLC2A1, and PPIG, which contribute to the tumour progression and resistance phenotype." (PMID 40004024, 2025).